ANXA2R-OT1 (ANXA2R overlapping transcript 1)
Synonyms: FLJ32255
Gene: Long non-coding RNA gene on chromosome 5 (42,918,237 to 43,067,492, reverse strand). Ensembl gene ENSG00000177738.
Diseases named in the same sentence as ANXA2R-OT1 in open-access papers:
ANXA2R-OT1 is named in the same sentence as 1 disease in open-access papers, as found by Europe PMC text mining. Sharing a sentence is not in itself a finding about the gene and the disease.
ANXA2R-OT1 shares sentences with these, for which no sentence is quoted: infarction (1 paper).